VIM (vimentin)
Diseases named in the same sentence as VIM in open-access papers (continued):
Sharing a sentence is not in itself a finding about the gene and the disease.
breast carcinoma (continued). "Vimentin staining and also filamentous actin (F-Actin) staining were much more intense and widespread in the FOXP3 knockdown cells, with the Vimentin staining in these cells resembling that of highly invasive BT549 breast cancer cells." (PMID 29963231, 2018). "Additionally, the EMT cell status of breast cancer cells was enhanced after treatment with either APRIL or BAFF (100 ng/ml), as depicted by an increase of vimentin/keratin staining ratio." (PMID 30131941, 2018). "As far as we know, no previous data exists on claudin in relation to vimentin, Zeb1 and Sip1 expression in breast cancers." (PMID 29482498, 2018). "These tests can be completed with CDX2 and CK19 for upper gastrointestinal tract, biliary ducts and pancreas, thyroglobulin for thyroid adenocarcinoma, NY-BR-1 and GATA-3 for female breast cancer, Mel-A, S100 and HMB45 for melanoma, and vimentin and Mel-A for kidney and adrenal gland tumors." (PMID 29116378, 2018). "However, to confirm that changes in Vimentin and E-cadherin expression were via direct regulation by ZEB2 and not by direct interactions with FOXP3 or miR-155, we then depleted the breast cancer cells of ZEB1 or ZEB2 using siRNAs." (PMID 29963231, 2018). "The expression of N-cadherin, vimentin, and Snail was not increased in heated breast cancer cells transfected with si-CTNNB1-1, meanwhile the down regulation of E-cadherin was also diminished." (PMID 29383144, 2017). "Since elevated vimentin and DAPK1 serum levels correlate postively with aggressiveness of breast cancer and are higher in “young” people, this might support the reasons why breast cancer in Ghanaian women tends to be more aggressive." (PMID 28616237, 2017). "Then we analyzed vimentin and E-cadherin expression by western blot to investigate whether MIAT induced breast cancer cell EMT." (PMID 29100300, 2017). "Moreover, lumican decreased the expression levels of the mesenchymal markers slug/snail-2 zeb1, vimentin and fibronectin and the epithelial marker E-cadherin in MDA-MB-231 breast cancer cells." (PMID 28332606, 2017). "Vimentin and DAPK1 should be explored further as potential breast cancer biomarkers in Africans." (PMID 28616237, 2017). "Moreover, the expressions of vimentin and SNAI2 were significantly downregulated after LDR exposure in these breast cancer cells." (PMID 28240233, 2017). "In particular, in breast cancer the transcription factor Forkhead box protein M1 (FoxM1) is known to induce EMT via SNAI2 (SLUG) promoter stimulation, while in pancreatic cancer, FoxM1 upregulates ZEB1, ZEB2, SNAI2 and vimentin." (PMID 28792442, 2017). "This mutation is abundant in breast cancers which are negative for oestrogen hormone receptor but DAPK1 and Vimentin expression profiles in breast cancer in African women are not known." (PMID 28616237, 2017). "Interestingly, FMRP was recently shown to promote breast cancer cell invasion and lung metastasis through regulation of specific mRNAs involved in EMT, including Vimentin mRNA47." (PMID 28698590, 2017). "Serum concentration of Vimentin and DAPK1 are elevated in Ghanaian breast cancer patients." (PMID 28616237, 2017). "Other groups reported that the breast cancer cells in epithelial to mesenchymal transition, would express both the PCK and Vimentin simultaneously, which might be the first signature of micrometastasis." (PMID 29259164, 2017). "In addition, MDA-MB-231 cells, a breast cancer cell line, also exhibited an MET phenotype when transfected with miR-1243, resulting in the upregulation of E-cadherin and the downregulation of Vimentin." (PMID 28638102, 2017). "We found that TF expression in breast cancer lines and tumors closely clustered with higher levels of EMT (high vimentin/low E-cadherin) and classical basal-type biomarkers KRT5, KRT14 and caveolin-1, while it clustered with lower levels luminal-type biomarkers KRT8, KRT18, ERBB3 and ESR1." (PMID 28938620, 2017).
breast carcinoma (continued). "We found that NLRP1 transfection promoted breast cancer cell line MCF-7 proliferation, migration, and invasion by possibly activating EMT and inflammasomes, mesenchymal markers vimentin, C-myc, MMP-9, and snail were upregulated, and then epithelial marker E-cadherin was downregulated." (PMID 29214170, 2017). "Breast cancer Met-1 cells were transducted with a DACH1 expression vector resulting in an ∼4.5-fold increase in DACH1 expression and subsequent reduction of CSC markers CD44, KLF4 and MYC as well as EMT markers including FN1 and VIM by mRNA analysis." (PMID 28659634, 2017). "Additionally, like genuine TNBC cells, 1° IRISOE mammary tumor cells show high level basal (e.g., CK5), EMT (e.g., vimentin) biomarker expression." (PMID 29262555, 2017). "Here, we found that LY6K downregulates the expression of E-cadherin in breast cancer cells, carcinomas and xenograft mice, whereas does not increase vimentin." (PMID 27494879, 2016). "We studied the location of vimentin in HNSCC and breast cancer cells." (PMID 27075696, 2016). "Hits capable of increasing vimentin in the mammary carcinoma-derived cell line MDA-MB-468 were confirmed in the non-tumorigenic breast-epithelial cell line MCF10A." (PMID 27876705, 2016). "Accordingly, treatment with low-dose (10–20 μg/mL) EtOAc extracts for 24 h decreased cell migration by downregulating protein expression of MMP2, MMP9, cyclin B, vimentin, and snail protein in MDA-MB-231 cells, indicating decreased breast cancer cell growth both in vivo and in vitro." (PMID 27078842, 2016). "Highly invasive breast cancer cells have been studied and selected, and these cells displayed EMT characteristics and dramatically enhanced invasive abilities with decreased levels of E-cadherin and increased vimentin, fibronectin, Twist and AKT2." (PMID 27453691, 2016). "Previous investigators proposed that vimentin, an intermediate filament protein, functionally contributes to EMT activation and is required for AXL upregulation, which contributes to the lung extravasation of breast cancer cells in mice." (PMID 27829217, 2016). "ERK5 activation results in significant decreased migration and invasion of both Hs578T and MDA-MB-231 breast cancer cells, whereas knockdown of ERK5 increases cell migratory and invasive capacities and Vimentin expression, indicating ERK5 as a negative regulator of EMT in these breast cancer cells." (PMID 25965818, 2015). "Importantly, the knockdown of Slug weakened the invasion ability of breast cancer cells and reversed the Jagged1-induced EMT process with significantly decreased expression of vimentin and increased expression of E-cadherin." (PMID 25645291, 2015). "One study showed that expression of c-ets-1 mRNA was associated with the EMT-derived phenotype typified by the expression of vimentin and the lack of E-cadherin in breast carcinoma cell lines." (PMID 25421630, 2015). "As vimentin elevation and E-cadherin repression are markers of EMT, our results suggested that Bmi-1 might play a role in regulation of EMT of breast cancer cells." (PMID 25734775, 2015). "Accordingly, overexpression of ADAM12L in these breast cancer cell lines did not modify E-cadherin and vimentin expression." (PMID 26407179, 2015). "To determine the potential role of Bmi-1 in regulation of IR-induced vimentin expression and EMT of breast cancer cells, we analyzed the correlation of the expression levels of Bmi-1 with vimentin and E-cadherin in MDA-MB-231 and Hs578t cells after IR (2 Gy) in a time-dependent manner." (PMID 25734775, 2015). "Importantly, specific downregulation of PD-L1 in claudin-low breast cancer cells showed signs of EMT reversal as manifested by CD44 and Vimentin downregulation and CD24 upregulation." (PMID 26245467, 2015). "The authors also reported vimentin rather than keratin expression in certain hormone-independent breast cancer cell lines, and in oncogene-transformed mammary epithelial cells." (PMID 24527079, 2014).
breast carcinoma (continued). "In ERα-negative breast cancer, we found TRPS1 to be positively associated with vimentin, SMA and slug." (PMID 24934762, 2014). "Vimentin and Notch protein expression was negative in noninvasive ductal carcinoma biopsies from breast cancer patients." (PMID 24527079, 2014). "As TRPS1 may be a critical regulator of EMT during breast cancer initiation and progression, the expression of EMT markers, including E-cadherin, β-catenin, vimentin, SMA and slug, were stained in human breast cancer TMA." (PMID 24934762, 2014). "The expression of EMT associated marker genes in ovarian cancer cells are similar to what we observed in MCF7 breast cancer cells, although the endogenous expression of vimentin in MCF7 was not detectable in KLF4-overexpressing or control cells." (PMID 25137052, 2014). "Vimentin protein expression in ducts in sections of biopsies from breast cancer patients was found to be negative for noninvasive ductal carcinoma, but positive for ductal carcinoma with invasive characteristics." (PMID 24527079, 2014). "This indicated that in addition to decreasing vimentin expression these pharmacological agents also downregulated MTHFD2 expression, which further validated our results on the connection between vimentin and MTHFD2 in breast cancer cells." (PMID 23295955, 2013). "Western blotting and immunofluorescence of suspended breast carcinoma cells revealed that vimentin intermediate filaments, but not cytokeratins, extend into McTNs and that vimentin-expressing breast cancer cell lines had higher McTN frequencies." (PMID 24240660, 2013). "Since vimentin plays a key role in EMT, we wanted to test if sWRE could inhibit EMT and EMT-induced motility in breast cancer." (PMID 24069380, 2013). "Though vimentin is widely studied in breast cancer, present study shows that change in motility or invasion were independent of vimentin expression." (PMID 23341946, 2013). "VIM and SNAI2 were highly expressed together with AXL in breast cancer cell lines MDA_MB_231, HS578T, and BT_549, for example, and may confer mesenchymal-like character to these lines." (PMID 22570691, 2012). "The primary breast cancer is usually positive for mammoglobin and GCDFP-15, which are negative in metastatic clear cell carcinomas or sarcomas (e.g., renal cell carcinomas, where is positive staining for vimentin and CD10)." (PMID 23050179, 2012). "Furthermore, RNAi-mediated knock-down of Pea3 in mouse mammary tumor cells leads to decreased expression of multiple PEA3 gene targets with established proneoplastic roles, including Cox-2, vimentin, Cyclin D3, HER2/neu and several MMP genes." (PMID 20107508, 2010). "The increase in vimentin expression may be due to the ~100-fold increase in ZEB2 expression, as ZEB2 is also involved in up-regulating the expression of vimentin in breast cancer cells." (PMID 19422694, 2009). "Foetal cells in the vicinity of breast carcinomas were not circulating leucocytes nor endothelial cells, but seemed mainly of mesenchymal or epithelial origin, because these expressed vimentin or cytokeratin, respectively." (PMID 18271969, 2008). "Indeed, in the current study, breast cancer with CD44hi/CD24lo cells showed a significant correlation with standard markers of EMT, specifically the upregulation of vimentin and downregulation of E-cadherin, which is consistent with previous reports on the relationship between EMT and CSCs." (PMID 40943144, 2025). "However, vimentin expression did not directly correlate with cell stiffness in the studied breast cancer cell lines." (PMID 39759848, 2025).
breast carcinoma (continued). "Immunohistochemical analysis was performed to evaluate the expression of vimentin, BMP-2, BMP-4, RANKL, Runx2, OPN, PTX3, and SDF-1, while Kaplan—Meier plots were used to assess their prognostic impact on overall survival in a dataset of 2976 breast cancer patients." (PMID 39859358, 2025). "Furthermore, exposure of tbLCM or loss of function of DACH1 in breast cancer cells significantly increased expression of KLF4, CD44 and Vimentin, indicating that one or more secreted factors in the LCM derived from TNBC tumor-bearing mice influences stemness/plasticity in breast cancer cells." (PMID 38581619, 2024). "EMT phenotype was further explored by protein detection of E-cadherin and vimentin, two critical markers of the epithelial and mesenchymal status in cancer cells and similarly reversed EMT signature was observed in two different mouse breast cancer models following clodronate treatment." (PMID 38169569, 2024). "Interestingly, our results show that Brazilin increases 50% in E-cadherin expression and decreases 50% in vimentin and Twist expression, MMPs, and cell invasion in triple-negative breast cancer (TNBC) MDA-MB-231 and to a lesser extend in MCF7 ER+ breast cancer cells." (PMID 38737746, 2024). "In breast cancer (BC), M2 macrophages produced CCL17 that induced EMT gene (N-cadherin, vimentin and PCNA) expression in tumors via CCL17/CCR4/mTORC1 axis." (PMID 38794298, 2024). "We observed that the expression level of ZEB2 and vimentin were greater in advanced stage (III & IV) tissues (n = 18) compared with early stage (I & II) tissues (p = .04), (p = .04), but E‐cadherin expression was decreased in the higher stage of breast cancer (p = .03)." (PMID 37088469, 2023). "Conversely, the reduction in Snail1, Vimentin and MMP-9 expression as well as the increase in E-cadherin expression in the MCF-7-liposome-si-CD147 group indicate that targeting CD147 could potentially reverse EMT in breast cancer cells." (PMID 38066486, 2023). "Moreover, to verify the effect of GREB1L on the metastasis ability of breast cancer cells in vivo, we detected the protein levels of epithelial-to-mesenchymal transition (EMT) marker genes, such as E-cadherin, N-cadherin, and vimentin, in tumors isolated from mice." (PMID 37964281, 2023). "Thus, we determined the expression level of well-known EMT markers, including E-cadherin, Snail, Vimentin, and Zeb1, through RT-qPCR and immunofluorescence assays to assess whether PNKY can induce EMT in breast cancer cells." (PMID 37104007, 2023). "In addition, the B7-H4 deficiency facilitates breast cancer cell growth, EMT and chemoresistance, with the opposite effects observed in the B7-H4 overexpression of breast cancer cells, including downregulation of migration and EMT critical genes such as vimentin and N-cadherin." (PMID 37794509, 2023). "As expected, the knockdown of Notch4 expression in TNBC cells enhanced Vimentin expression, a mesenchymal status marker, and E-cadherin expression, an epithelial status marker, indicating that depletion of Notch4 expression in TNBC cells boosted breast cancer metastasis." (PMID 37149651, 2023). "Therefore, we tested the expression of various EMT‐related proteins in breast cancer cells and observed that the levels of several EMT markers, including slug, snail, and vimentin, were increased in CASQ2‐overexpressing cells and the level of ZEB1 was decreased." (PMID 34743414, 2022). "We included four luminal (MCF-7, T47D, ZR-75-1, MDA-MD-134 VI), one HER2-positive (SKBR-3), eight basal Vimentin-positive (MDA-MB-436, MDA-MB-231, HCC38, HCC1395, BT459, CAL-51, HDQ-P1, and Hs578T), and two basal Vimentin-negative breast cancer cell lines (DU4475, HCC1806), fibroblasts, and PBMCs." (PMID 35140234, 2022).
breast carcinoma (continued). "In addition, EMT biomarkers CDH1 and VIM were highly expressed in cancer cells, consistent with previous reports showing that TAM promoted EMT progress of cancers (lung cancer, colorectal cancer, breast cancer and ovarian cancer) by SPP1." (PMID 36148946, 2022). "Additionally, the downregulation of NEAT1 induced the expression of N-cadherin and vimentin, but repressed that of E-cadherin, indicating that NEAT1 may inhibit the EMT process in breast cancer cells." (PMID 36613528, 2022). "To assess the generality of our findings, we explored the effect of mechanical compression on the nonmetastatic mouse breast cancer cell line 67NR, which is derived from the same primary breast cancer as 4T1 and expresses N-cadherin and vimentin, but not E-cadherin." (PMID 36268514, 2022). "Additionally, 60 FFPE breast cancer tissues obtained from the Second Hospital of Dalian Medical University were inspected with immunohistochemical staining to confirm the relevance between HRD1 and Vimentin expression." (PMID 33530981, 2021). "The study conducted on MDA-MB-231 and its derived breast cancer stem cells (BCSC) revealed that the anti-metastatic effect of curcumin was induced through the regulation of EMT-related markers, including β-catenin, vimentin, E-cadherin, N-cadherin, and fibronectin." (PMID 34298639, 2021). "Similarly, a subset of equine mammary carcinomas exhibit oestrogen receptor alpha positivity by immunofluorescence, which has been suggested to correlate with weak or absent expression of vimentin." (PMID 33280071, 2021). "Similar in vitro morphological changes, accompanied by increased vimentin and N-cadherin, and decreased E-cadherin mRNA and protein levels, have been reported to be activated by LIF in the human CRC cell line HCT116 and in epithelial-like T47D and MCF7 breast cancer cell lines in vitro." (PMID 34361105, 2021). "In order to examine whether or not 5-Aza-CdR treatment led to the transition between epithelial and mesenchymal status in breast cancer cells, we treated MCF7 cells with various concentrations of 5-Aza-CdR and analyzed the expression level of E-cadherin and vimentin." (PMID 32193333, 2020). "Taken together, our results show that Akt-mediated phosphorylation of TWIST1 can revert the nonmetastatic phenotype of breast cancer cells into metastatic phenotype and changes in expression of vimentin and N-cadherin may not be enough to explain EMT." (PMID 32922123, 2020). "To assess whether DANCR regulates EMT or cancer stemness of malignant breast cancer cells, we first examined the expressions of EMT‐related biomarkers, including SNAIL1, SLUG, MMP‐2, MMP‐9, E‐cadherin, and Vimentin in shDANCR vs. shNC (MDA‐MB‐231 and MDA‐MB‐468) cells." (PMID 31860165, 2020). "Similarly, other subtypes of breast cancer cell lines including MCF-7 (luminal type), and MDA-MB-231 (basal type) also showed a decrease of E-cadherin and an increase of N-cadherin with Vimentin with IL-6 exposure while S-HBCC (cancer stem cell type) was not showed significant change." (PMID 33659239, 2020). "Similarly, reduced E-cadherin and CD24 and increased vimentin, CD44, and Snail were also observed in MDA-MB-468 cells – another PTEN-negative breast cancer cell line with a 44-bp deletion in the PTEN gene, which results in frameshifting and loss of the PTEN protein 18,52." (PMID 32728066, 2020). "Similarly, higher expression of SCRIB was associated with poor prognosis of estrogen receptor-negative and vimentin-positive breast cancer subtypes and clear cell renal cell carcinoma patients." (PMID 32564009, 2020). "Notably, the mRNA levels of the mesenchymal markers SLUG, SNAI1, VIM, and NCAD were increased by ectopic GREM1 expression or exogenous rhGrem1 treatment, suggesting that Grem1 induces a slightly more mesenchymal phenotype in these breast cancer cells." (PMID 31533776, 2019).